CD27 (CD27 molecule)
Diseases named in the same sentence as CD27 in open-access papers (continued):
Sharing a sentence is not in itself a finding about the gene and the disease.
infection (continued). "As expected no major alteration in the composition of pre-immune and infection-induced early myeloid subsets was recorded in the absence of IFN-γ signaling for “CD27+ CMPs” (39.3±12.3% of LIN−c-Kit+CD27+ cells) or “GMPs” (34.3±13.0% of LIN−c-Kit+CD27+ cells)." (PMID 23762028, 2013). "With regard to HCV-infection, while HCV resolvers showed an accumulation of VH1-69 CD27− B-cells compared to HCV-chronic patients, in MC condition a reduced number of naïve B-cells (CD27−, CD21+, and CD10−) due to an increasing sensitivity to undergo apoptosis was found." (PMID 22952554, 2012). "Among untreated persons at this early infection time-point with high CD8+ T cell activation levels, we observed a greater fraction of both total and HIV-1 gag specific CD8+ T cells fall into the intermediate memory (CD27+CD28−) phenotype." (PMID 19198651, 2009). "The naive B cell subset (CD19+CD21+CD27+) was not significantly different between symptomatic and asymptomatic individuals, and the relative abundance of this subset was observed to decrease with time throughout the infection." (PMID 39052480, 2024). "The frequencies of classical memory (CD45+ CD19+ CD21+ CD27+) and activated memory B cells (CD45+ CD19+ CD21- CD27+) and plasma (CD45+ CD19+ CD21- CD20-) cells were significantly elevated, with a twofold increase among the vaccinated population in comparison to the naturally infection group." (PMID 39205152, 2024). "We found that predominance of metabolically active Ag+ CD4+,CD27+,PD-1dim CD57dim T cells and CD8dim,CD11c+ Ag+ T cells correlates with the absence of breakthrough infection and may thus confer high immune protection." (PMID 38553477, 2024). "When we further analyzed the specific CD27+ memory B cell subsets, we found that Wuhan Hu-1 RBD-specific CD27+ memory B cells and, in particular IgG+CD27+ and IgA+CD27+, but not IgM+CD27+, were significantly higher at 9 months in previously infected subjects compared to infection-naïve subjects." (PMID 36926327, 2023). "However, it has been suggested that a subset of CD27+ KLRG1+ NK cells expand following BCG inoculation and confer protection against M. tuberculosis infection by reducing the CFU numbers in the lungs at 30 days post-infection." (PMID 37486946, 2023). "This negative impact of DON on CD8α and CD27 expression levels could lead to a partial impairment of T-cell stimulation and a suboptimal T-cell response following vaccination or infection of pigs." (PMID 31694331, 2019). "Though we did find a significantly increased proportion of mature (CD27–CD11b+) mouse NK cells at d2 post-infection in comparison to d3 post-infection, this partial alteration in maturation is unlikely to be solely responsible for the abrogation of IFN-γ production at d3 post-infection." (PMID 31214198, 2019). "Although Tfh cells were able to infiltrate the spleen during acute VL, they were mostly absent at the chronic phase, paralleling the decline in CD27+ memory B cells and specific IgG, suggesting an inability to maintain a sustained Tfh response during the chronic phase of infection." (PMID 30090101, 2018). "The optimal infection time was set up after 48 hours of OKT3 activation, since at this time point we obtained the highest percentage of CAR-expressing T cells, and a less differentiated phenotype, as assessed by the high expression of CD27, CD28 and CD62L markers (central panel)." (PMID 25279468, 2014). "In order to identify the phenotype of CD8+ T cells generated during this infection/cure under CQ cover regimen, splenocytes and peripheral blood from mice three weeks post last inoculation for the presence of CD8+, CD3+, CD11a, CD127, CD27, KLRG1, CD44 and CD62L cells by flow cytometry was analysed." (PMID 24620841, 2014).
infection (continued). "Alternatively, the heterogeneous expression of CD27 and PD-1 in LTBI and BCG groups may reflect the inherent phenotypic differences between the immune responses induced by Mtb and BCG at the time of infection or vaccination, which result in long-lived antigen-specific memory responses." (PMID 22545156, 2012). "Additionally, CD27 expression was noted in a subset of IFNγ producing γδ T-cells following infection, while CD27 negative γδ T-cells did not produce IFNγ, suggesting a role for CD27 in regulation of interferon and specific cytokine production in immune responses." (PMID 34630390, 2021). "In addition, given that we found EBERs+/CD27+ cells only in 4 patients, and 3 of them also had EBERs+/IgD+ cells, EBV presence in memory B-cells could be a consequence either of direct infection, or of a previous naïve infected B-cell which maturated to memory B-cell." (PMID 26988293, 2016). "This propensity for CD27 expression was most pronounced for IFN-γ-producing CD8+ T cells and may be related to better survival and memory transition, supported by the high frequencies of IFN-γ-producing CD8+ T cells both in the acute phase and 5 weeks after clearance of infection." (PMID 27512056, 2016). "CD8 T cell activation was accompanied by depletion of CD8 T-cells with a resting (CD27+CD28+) phenotype without accumulation of partially (CD27−CD28−) or fully (CD27−CD28−) differentiated phenotypes indicating that differentiated effectors migrate to the site of infection." (PMID 22363665, 2012). "The frequency of switched CD27+ MBCs affected the antibody response in vaccinated, but not in convalescent CVID, patients, pointing out that natural infection can induce an antibody response also in those having a severe B memory cell defect." (PMID 34831138, 2021). "Initiation of ART in early infection is able to largely normalize the proportion of CD8+ CD28−, CD57+, and CD27− T cells, though not to the levels seen in age-matched HIV-seronegative individuals." (PMID 30863403, 2019). "Strikingly, we found that the infection with HeV and NiV-B did not modify the expression levels of lymphocyte markers (CD2, CD3D, CD3E, CD3G, CD4, CD8A and CD27) in the lung tissue by 5 dpi." (PMID 29538374, 2018). "At 5 days post-infection, Granzyme B+CD4+ T cells up-regulated the adhesion molecule CD44, but expressed neither the co-stimulatory receptor CD27 nor the memory T cell marker CD127 (a subunit of interleukin-7 receptor-α)." (PMID 24367519, 2013). "Despite cytotoxic activity and cytokine production ex vivo, these TRMs demonstrated reduced CD27 expression and proliferation and failed to control EBV viral loads in the NALT during infection, although effector memory T cells (TEMs) controlled viral titers in spleen and blood." (PMID 39264727, 2024). "However, in LM-GP33 infection at day 7, CD43 and CD27 expression did not explicitly mirror the phenotype observed by CD127 and KLRG1 expression." (PMID 38127070, 2023). "In the scRNA-seq dataset, CD21+CD27+ resting Bm cells were the main S+ Bm cell subset at months 6 and 12 post-infection in nonvaccinated individuals, whereas CD21–CD27+CD71+ activated and CD21–CD27–FcRL5+ Bm cells became predominant post-vaccination at month 12 post-infection." (PMID 37106039, 2023). "However, we observed higher frequencies of immature CD27+CD11b- NK cells in Ifnar1ΔNKp46 compared to Ifnar1fl/fl mice, suggesting a defect in the ability of NK cells to mature in response to ECTV infection in the absence of intrinsic IFNAR signaling." (PMID 34015056, 2021). "Here we have refined the phenotype-based isolation of early myeloid subsets in the HPC compartment by co-staining with CD27, a member of the TNF-receptor superfamily present on a subset of HSCs and all LMPPs, which did not exhibit any regulation of its surface amount during infection." (PMID 23762028, 2013).
cancer (171 papers, 2003 to 2026). A tumor composed of atypical neoplastic, often pleomorphic cells that invade other tissues. "To gain a deeper understanding of the underlying mechanism behind the immune suppression of CD27 signaling, we investigated the association between CD27 expression and a variety of immunological checkpoint markers in 33 different cancer types." (PMID 38169519, 2024). "Regarding its role as a predictive/prognostic biomarker, studies outside and within the cancer spectrum show its relevance, with higher levels of soluble CD27 in peripheral blood mostly being associated with worse outcome of patients." (PMID 39511626, 2024). "Our data showed TMB was favorably linked with CD27 expression in three different cancer types, including LAML, LGG, and UCEC." (PMID 38169519, 2024). "At least one MMR-related gene was shown to be linked with CD27 expression in 27 of the 33 cancer types studied." (PMID 38169519, 2024). "Through correlation analysis, we discovered in this study that CD27 expression was strongly correlated with the mutation levels of 5 MMR genes in human pan-cancer." (PMID 38169519, 2024). "The CNV gain in the 43 kb region in 12p13.31 in 601covers the genes SCNN1A, LTBR and CD27 and CD27 overexpression has been found to be associated with the development of different cancers." (PMID 30975103, 2019). "Higher CD27 levels were associated with NK cells that are less effective at killing cancer cells." (PMID 40805205, 2025). "Notably, CD27 expression was linked with prognosis in a several of Kaplan-Meier cumulative curves for cancers in the TCGA database." (PMID 38169519, 2024). "In most malignant tumors, CD27 expression was associated with MLH1 expression." (PMID 38169519, 2024). "The positive association between CD27 and TIGIT, CD48 in the majority of cancers suggested a complete co-expressing landscape, and our data demonstrated that CD27 expression was strongly connected with various immunological checkpoints in varied immunocytes and unique T cells." (PMID 38169519, 2024). "MMR mutations in cancer cells may be the direct cause of CD27 expression and function abnormalities." (PMID 38169519, 2024). "The CD27 is expressed in cancer, which is related to different mutation patterns." (PMID 38169519, 2024). "Adoptive transfer of TILs possessing properties of less differentiated T cells, such as high surface expression of the costimulatory molecules CD28 and CD27 and long telomeres (>5 kb), is associated with their increased persistence in vivo and correlates with objective cancer regression." (PMID 21827675, 2011). "This cell-type specificity may explain why CD27-targeted therapeutic strategies are associated with lower risks of systemic adverse reactions, echoing recent experiences in cancer immunotherapy, where targeting costimulatory/coinhibitory molecules typically results in manageable safety profiles." (PMID 41202080, 2025). "Tumors indeed can promote the immunosuppressive effects of the CD27-CD70 co-stimulatory axis, and CD27 has been a target for immune checkpoint blockade in cancer." (PMID 41878425, 2026). "Cancer‐associated genes (VIM, IGHG1‐4, IGKC, IGHA1) were upregulated, and CPCAT data revealed correlations of IREB2 with IGHG1 and VIM, and CD27 with IGHG1." (PMID 41377765, 2025). "At the same time, the exhaustion of B cells (characterized by high expression of CD21 and CD27) correlates with the cancer progression." (PMID 40136652, 2025). "Varlilumab(anti‐cancer) stimulates the CD27 pathway for T cell activation and effector cell recruitment for antitumor activity." (PMID 40988381, 2025). "Despite their low abundance, CD27+ IFNγ-producing γδ T cells provide significant protection from pathogens and cancer." (PMID 38816652, 2024). "In these cancers, CD27 expression was positively correlated with immune and stromal scores, and this correlation is statistically significant." (PMID 38169519, 2024).
cancer (continued). "The results of immunohistochemistry showed that CD27 was highly expressed in most cancers compared to normal tissues, which was consistent with mRNA expression profiles in TCGA and GTEx databases." (PMID 38169519, 2024). "CD27 was found to play a aggressive role against the prognosis of eleven distinct cancers, which included CESC, HNSC, SKCM, BLCA, CHOL, OV and ACC." (PMID 38169519, 2024). "Then, we compared baseline soluble CD27 (sCD27) concentrations between cancer patients and healthy controls and demonstrated that these were significantly higher in cancer patients." (PMID 39511626, 2024). "This helps us screen for high-value cancers targeted by the CD27 and provide constructive advice on their treatment." (PMID 38169519, 2024). "We found that CD27+ Ly6C− cells convert into CD27+Ly6C+ cells, and these CD27+Ly6C+ cells control cancer progression in mice, while the CD27+Ly6C− cells cannot." (PMID 38816652, 2024). "We further examined the possibility of an association between CD27 expression and MSI and we found that MSI was substantially linked with CD27 expression in 10 different kinds of cancer." (PMID 38169519, 2024). "The TCGA and GTEx databases were used to analyze differences of CD27 expression in 33 cancers, the data from these two databases formed a mutually validated comparison." (PMID 38169519, 2024). "Our study confirms that activation of the CD27 is positively correlated with CD8+T cells in almost all cancers." (PMID 38169519, 2024). "In UVM, we found that the expression of CD27 initiates the NK cell activation pathway, which is inconsistent with the landscape in other cancers." (PMID 38169519, 2024). "To further explore the role of the CD27 in regulating cancer progression, we analyzed its effect on TIICs." (PMID 38169519, 2024). "Combining the two into a promising "multi-CD27 score" will provide a better representation of the highly complex cancer-patient network, allowing the development of a highly relevant biomarker for ICI therapy." (PMID 39511626, 2024). "We analyzed OS, DSS, DFI, and PFI in pan-cancer to determine the roles CD27 played in the prognosis, furtherly." (PMID 38169519, 2024). "In this work, we studied the prognostic relevance of the expression of CD27 in 33 different cancer types." (PMID 38169519, 2024). "First, we evaluated the CD27 expression differences in 33 cancers and came to meaningful conclusions." (PMID 38169519, 2024). "Nevertheless, we observed expression of CD27, CD28 and CD62L on many TAII cells, which have been associated with clinical responses and high anti-cancer activity and persistence." (PMID 38184565, 2024). "We tested the functional consequence of IL-27 treatment on CD27+Ly6C+ γδ T cells in cancer cell line-killing assays." (PMID 38816652, 2024). "The results showed that CD27 have a significant high expression profile in the vast majority of cancer samples." (PMID 38169519, 2024). "Addressing this question, the current study provides evidence that peripheral CD27+ IFNγ-producing γδ T cells consist of an immature Ly6C− population that converts into a mature Ly6C+ population with cancer cell killing capacity." (PMID 38816652, 2024). "Taken together, these data show that CD27+Ly6C+ γδ T cells are inherently superior over CD27+Ly6C− γδ T cells at killing cancer cells." (PMID 38816652, 2024). "For CD27+Ly6C+ γδ T-cell-cancer cell co-cultures, we obtained mixed results for the three cell lines." (PMID 38816652, 2024). "Further investigation into the link between TME and CD27 expression in various cancer types would be extremely appropriate given that our findings have verified the predictive significance of CD27 in pan-cancer." (PMID 38169519, 2024). "Similar trends were observed in GATA6high carcinoma-infiltrated ROIs, including increased CD27+ activated T cells and decreased CTLA4+ cells (p.adj = 0.003)." (PMID 38733987, 2024).
cancer (continued). "Many different types of cancer, both hematologic and solid, have been linked to abnormal expression of CD70 and its receptor CD27." (PMID 37849799, 2023). "Taken together, we present the in vitro characterization of a novel bispecific antibody that re-activates T cell immunity in EGFR-expressing cancers through targeted co-stimulation of CD27." (PMID 37545491, 2023). "By targeting EGFR, which is commonly expressed on carcinomas, CD27xEGFR induced cancer cell-localized crosslinking and activation of CD27." (PMID 37545491, 2023). "Anti-cancer therapeutics based on exploiting CD27-mediated T cell co-stimulation have proven safe, but clinical responses remain limited." (PMID 37545491, 2023). "On the other hand, soluble CD27 is reduced in the serum of cancer patients compared to healthy individuals, while in the serum of cancer patients post immunotherapy, soluble CD27 correlates with improved survival probability." (PMID 37391708, 2023). "In line with this, CD27xEGFR demonstrated selective and simultaneous binding to EGFR and CD27, with clear doublet formation of carcinoma and T cells and inhibition of binding upon pre-incubation with excess amounts of mAb 425 and CD27 mAb." (PMID 37545491, 2023). "Agonistic mAb targeting co-stimulatory molecules of the tumour necrosis factor receptor superfamily (TNFRSF) (e.g. OX40, CD40, 4-1BB, GITR or CD27) are attractive candidates for cancer immunotherapy." (PMID 35288635, 2022). "The associations of P4HA1 expression with LAG3, ICOS, CTLA4, CD48, TNFSF14, and CD27 expression were inconsistent among cancer types." (PMID 35812752, 2022). "CD27 is a new ICI that is being investigated in phase I/II clinical studies for a variety of cancer types, with encouraging results." (PMID 35804895, 2022). "We have reported that CD27 is expressed at differential levels among T cell subtypes in the peripheral blood of cancer patients, and in the blood and lymphoid tissues of human CD27 transgenic mice (hCD27Tg), with the highest expression level on Treg." (PMID 34028568, 2022). "To further explore the mechanism underlying CD27 and PDL2 with NSCLC invasion, we identified the association between CD27/PDL2 expression and cancer invasion signature (CIN25) in LUAD from TCGA database." (PMID 35874720, 2022). "Targeting/blocking CD70/CD27 signalling thus represents an attractive therapeutic strategy for multiple types of cancers." (PMID 36471481, 2022). "The functional validation using TCGA data indicated that CD27 and PDL2 expression is significantly associated with cancer invasion signature, which illustrated potential mechanisms." (PMID 35874720, 2022). "The research on CD27 seems to be even more important because in the context of an effective cancer vaccination, CD27 agonism with anti-PD-1 therapy further improves treatment efficacy." (PMID 35204342, 2022). "CD27 and PDCD1LG2 (PDL2) showed significant association with cancer invasion signature in TCGA dataset." (PMID 35874720, 2022). "Here, we investigated the influence of mAb isotype and epitope specificity in agonistic CD27 mAb therapy for cancer." (PMID 35288635, 2022). "Correspondingly, exploiting TNFRSF-mediated signaling for cancer immunotherapy has been a major field of interest, with various therapeutic TNFRSF-exploiting anti-cancer approaches such as 4-1BB and CD27 agonistic antibodies being evaluated (pre)clinically." (PMID 35053463, 2022). "A number of T cell costimulatory molecules including CD137, OX40, CD40, ICOS, GITR, and CD27 are being targeted pharmacologically with agonists to improve outcomes in cancer patients." (PMID 34290245, 2021). "Among all the significant associations, CD36 expression was positively correlated with CD27, CD28, CD40, and ICOS in multiple cancer types, but negatively associated with CD40 in TGCA." (PMID 34234847, 2021). "Agonistic antibodies targeting costimulatory receptors of the TNFR family, such as 4‐1BB and CD27, have entered clinical trials in cancer patients." (PMID 33180337, 2021).